MELK (maternal embryonic leucine zipper kinase)
Diseases named in the same sentence as MELK in open-access papers (continued):
Sharing a sentence is not in itself a finding about the gene and the disease.
cancer (continued). "In CRC, MELK expression was found to be significantly higher in tumor specimens compared with healthy tissue and may contribute to cell cycle progression and cancer development." (PMID 36591473, 2022). "Interestingly, MELK is overexpressed with high proliferation index in many cancers including breast, ovarian, brain, colorectal, gastric, and blood cancers." (PMID 35749404, 2022). "MELK is frequently overexpressed in cancer, which makes it a promising target in cancer therapy." (PMID 34550356, 2021). "Nevertheless, the underlying mechanism and biological significance of MELK, particularly in the cancer stem cells and EMT, are not yet clear." (PMID 33962400, 2021). "Indeed, MELK was shown to increase the tolerance of cancer cells to the DNA damage response by inhibiting the phosphorylation of ATM." (PMID 33431809, 2021). "The deletion or inactivation of MELK leads to abnormal cell division and apoptosis in cancer cells." (PMID 34671205, 2021). "The DGE analysis showed the genes PKMYT1, and MELK upregulated in 17 and 16 cancers, respectively." (PMID 33801837, 2021). "Altogether, our work could provide a new angle of how to target MELK overexpressing cancers and might thus lead to novel intervention strategies in the future." (PMID 34550356, 2021). "Because of these combined observations, MELK is considered a highly selective cancer target." (PMID 34550356, 2021). "However, two recent articles questioned the role of MELK in cancer development since, contrary to siRNA, disruption of MELK using the CRISP-Cas9 approach had no appreciable impacts on tumor cell growth." (PMID 33431809, 2021). "The generation of in vitro cancer model, while using CRISPR/Cas in mammalian cell lines with single or multiple gene(s) deletions is now easy and feasible, such as CRISPR-based mediated silencing of MELK, a cancer drug (OTS167) target in several clinical trials." (PMID 33748164, 2021). "MELK, as a member of kinases family which is directly regulated by the FOXM1 transcription factor, has been proven to function as an oncogenic gene that is closely associated with mitotic progression as well as the proliferation in multiple human cancers." (PMID 33061942, 2020). "MELK as an important cancer stem cell marker was highly expressed in GSCs, which may be one of the reasons why GSCs is more sensitive to OTSSP167." (PMID 33520717, 2020). "Furthermore, elevated MELK protein expression was correlated with decreased overall survival and disease-free survival in various types of human cancer." (PMID 32047721, 2020). "Importantly, it was recently demonstrated that MELK function is required for clonogenic growth of TNBC-derived cells, and this has made MELK a target for the development of novel cancer therapeutics." (PMID 32946434, 2020). "In light of these findings, suppression/inactivation of MELK may be an attractive therapeutic strategy in cancer." (PMID 31861475, 2019). "Recent studies have identified the expression of MELK in a large scale of cancers." (PMID 31380279, 2019). "Inconsistent with our data, authors suggested that MELK might be upregulated in cancer cells and its function in cell cycle progression might be redundant with other kinases." (PMID 31380279, 2019). "Due to the established role of MELK in promoting DNA repair and genome integrity, we hypothesized that cancer cells depleted of MELK might be more vulnerable to DNA insults than the corresponding cells retaining MELK activity." (PMID 31861475, 2019). "Thus, to address the functions of MELK in cancer more precisely, either MELK genetically engineered mouse models and/or selective inhibitors of this protein should be used." (PMID 31861475, 2019). "We then tested whether MELK protein was also overexpressed in human cancers using a tissue microarray." (PMID 29437778, 2018). "Novel MELK inhibitor OTSSP167 is shown to reduce growth of various cancer types." (PMID 29416794, 2018).
cancer (continued). "Interestingly, MELK is additionally involved in the initiation and propagation of numerous human cancers and correlates with poor prognosis." (PMID 30517191, 2018). "Moreover, knockdown of MELK using RNA interference (RNAi) has been reported to block cancer cell proliferation and trigger cell cycle arrest or mitotic catastrophe." (PMID 29417930, 2018). "We believe that, if MELK does play a role in cancer, it may be detectable only in very limited circumstances, and likely in vivo." (PMID 29417930, 2018). "We note that MELK expression is cell cycle-regulated, peaking in mitosis, and gene signatures that capture mitotic activity have been found to be prognostic in multiple cancer types." (PMID 29417930, 2018). "MELK has been shown to promote cancer cell survival and tumor cell differentiation." (PMID 29416794, 2018). "Future synthetic lethal screening and additional in vivo assays may clarify what role, if any, MELK plays in cancer biology." (PMID 29417930, 2018). "Further study is needed to clarify the role of MELK in different cancer types." (PMID 29416794, 2018). "This was similar to results reported in other MELK‐positive cancer cell line models." (PMID 29437778, 2018). "If MELK plays no overt role in cancer biology, then why would MELK expression be linked with death from cancer?" (PMID 29417930, 2018). "Furthermore, although MELK has been suggested to form a heterotrimeric protein complex with the oncogenic transcription factors c-Jun and FoxM1 in cancer stem cells, MELK lacks the binding ability in normal progenitor and stem cells." (PMID 29416794, 2018). "We further demonstrated that controlling for cell proliferation ablates the prognostic significance of MELK expression, suggesting that this link may explain its connection with outcome in cancer." (PMID 29417930, 2018). "Furthermore, they observed that cancer cells depleted of MELK by CRISPR editing were found to retain sensitivity to the MELK kinase inhibitor OTS167." (PMID 29417929, 2018). "If these unbiased screens indicated that cancer cell lines required MELK expression to proliferate, then that would bolster the contention that MELK could be a therapeutic target in cancer." (PMID 28337968, 2017). "With the recent development of inhibitors, additional MELK inhibition may also be a therapeutic option in patients with PD-L1 amplified cancers." (PMID 29212506, 2017). "It is supposed that MELK (maternal embryonic leucine zipper kinase) plays critical roles in many aspects including cell cycle, cell proliferation, embryogenesis and oncogenesis due to its overexpression in many kinds of cancers." (PMID 29100313, 2017). "MELK is expressed in the mouse egg and preimplantation embryo and may regulate proliferation of cancer stem cells." (PMID 29216888, 2017). "Moreover, overexpression of MELK is observed in cancer stem cells, associated with undifferentiated phenotype, poor prognosis, and chemo and radioresistance." (PMID 28926338, 2017). "The top one gene, MELK was upregulated in 73.1% samples and across 12 cancer types." (PMID 28489584, 2017). "At the protein level, MELK is hyperphosphorylated, and reaches its maximal abundance and kinase activity during M phase in both Xenopus embryos and human cancer cell lines." (PMID 28926338, 2017). "Furthermore, many publications have reported that knocking down MELK using RNAi inhibited the proliferation of cell lines derived from these cancer types." (PMID 28337968, 2017). "Unexpectedly, we found that mutating MELK failed to affect the growth of every cancer cell line that we tested." (PMID 28337968, 2017).
cancer (continued). "Additionally, four clinical trials have been launched to test the MELK inhibitor OTS167 in human cancers (NCT01910545, NCT02768519, NCT02795520, and NCT02926690)." (PMID 28337968, 2017). "At a minimum, our results suggest that MELK is dispensable for mitotic progression in most cancers." (PMID 28337968, 2017). "Recent research has explored the role of MELK in cancer stem cell maintenance and survival." (PMID 26701722, 2016). "High level of MELK expression has been reported in cancers and cancer stem cells." (PMID 27082996, 2016). "The two molecules, TOPK and MELK, have shown similar expression patterns; they are up-regulated in various types of cancer including cancer stem cell-enriched tumors and more importantly their expressions are hardly detectable in normal organs except in the testis." (PMID 26933922, 2016). "Furthermore, MELK has been reported to act during cytokinesis in Xenopus early embryos and in human cancer cells." (PMID 27082996, 2016). "Hence, therapeutic strategies to target the MELK in CSCs should overcome the drawbacks of the conventional anti-cancer therapies." (PMID 26871945, 2016). "MELK activity modulates many cellular and biological processes, including proliferation, apoptosis, hematopoiesis and oncogenesis, and is believed to have a critical role in cancer stem cell maintenance." (PMID 27540718, 2016). "In addition, MELK expression was also elevated in cancer stem cells and overexpression of MELK was shown to enhance spheroid formation of cancer cells." (PMID 26918358, 2016). "In addition, we performed comprehensive analysis of the MELK expression in various cancer cell lines using gene expression datasets from the Cancer Cell Line Encyclopedia (CCLE)." (PMID 26871945, 2016). "In addition, public datasets revealed very high level of MELK expression in SCLC among 33 different cancer types examined." (PMID 26871945, 2016). "We found that expression of MELK and stem cell marker proteins was higher in in vivo A549 xenograft tissues than in vitro cultured cells, further suggesting previous results that cancer stem cells expressing MELK at high level have the growth advantage in vivo." (PMID 26918358, 2016). "Furthermore, recent studies revealed upregulation of MELK in cancer stem cells and indicated MELK as a potential marker for cancer stem cells." (PMID 26918358, 2016). "Hence, we have developed TOPK inhibitors (OTS514 and OTS964) and a MELK inhibitor (OTS167) that showed therapeutic potentials in pre-clinical models of human cancer." (PMID 26933922, 2016). "Interestingly, MELK is additionally involved in the development of numerous human cancers, tumor initiation, and tumor propagation." (PMID 25852826, 2015). "MELK is expressed in several human cancers and stem cell populations." (PMID 25852826, 2015). "MELK has been shown to be differentially expressed in cancer stem cells." (PMID 25852826, 2015). "Unique spatial and temporal patterns of expression within these tissues suggest that MELK plays a prominent role in cell cycle control, cell proliferation, apoptosis, cell migration, cell renewal, embryogenesis, oncogenesis, and cancer treatment resistance and recurrence." (PMID 25852826, 2015). "Together, these studies suggest MELK may have a critical role in promoting apoptosis in developmental models and some forms of cancer." (PMID 25852826, 2015). "Conclusions derived from these studies suggest that MELK provides a unique growth advantage in cancer, and that it may be doing so by playing an important in maintaining the properties of the cancer stem cell population." (PMID 25852826, 2015). "Indeed, MELK has recently emerged as an oncogene and a biomarker overexpressed in multiple cancer stem cells, and so is considered a potential therapeutic target." (PMID 24885567, 2014). "Previous studies also suggested that MELK expression was elevated in cancer stem cells (CSCs) and could promote CSCs growth, differentiation and self-renewal." (PMID 24885567, 2014).
cancer (continued). "Furthermore, MELK expression is correlated with a poor prognosis of a variety of cancers, including GBM." (PMID 24739874, 2014). "We postulate that C1 may also effectively treat a variety of cancers with elevated activation of MELK." (PMID 24739874, 2014). "Given that JNK signaling orchestrates a variety of cellular processes, pharmacological inhibition of MELK, a more downstream and possibly cancer-specific protein, may lead to fewer off-target effects and greater specificity in targeting cancer cells." (PMID 24739874, 2014). "The expression levels of other mitotic factors including Cyclin B1 and Aurora A are comparable between basal-like and luminal cancer cells, suggesting that MELK may play a unique role during mitosis in BBC cells." (PMID 24844244, 2014). "Knockdown of MELK inhibited proliferation, colony formation and survival of cancer stem cells." (PMID 24885567, 2014). "Further investigation on MELK as a cancer therapeutic target is needed." (PMID 24185907, 2013). "Indeed, several studies have shown that MELK expression is dramatically increased in cancers of various tissue origins." (PMID 24167714, 2013). "This, together with the data showing a decrease in cell proliferation of some cancer cell lines after MELK knockdown by siRNA, has led to the hypothesis that the high levels of MELK activity may provide an advantage to tumor cells." (PMID 24167714, 2013). "Thus, MELK is a promising drug target for cancer treatment and an important prognosis marker for some cancers." (PMID 23922895, 2013). "The regulation of MELK in cancers and its potential as a therapeutic target were also described." (PMID 24185907, 2013). "MELK is initially cloned in oocytes and detected both in normal tissues and in cancer cells." (PMID 24185907, 2013). "In general, the effects of multiple protein interactions with MELK are oncogenic in nature, and the overexpression of MELK in kinds of cancer provides some evidence that it may be involved in tumorigenic process." (PMID 24185907, 2013). "The structural and biochemical features of MELK provide a better understanding of the regulation of this important protein kinase and may facilitate the development of specific MELK inhibitors for cancer treatment." (PMID 23922895, 2013). "MELK has emerged as a potentially important therapeutic target in the field of cancer research." (PMID 24167714, 2013). "This MELK inhibitor should be a promising compound possibly to suppress the growth of tumor-initiating cells and be applied for treatment of a wide range of human cancer." (PMID 23283305, 2012). "Hence, we investigated possible involvement of PSMA1 phosphorylation by MELK in the maintenance of cancer stem cell characteristics." (PMID 23283305, 2012). "MELK was also reported to be highly upregulated in multiple types of human cancer." (PMID 23283305, 2012). "In addition to the involvement in cancer cell growth, MELK was also reported its critical roles in formation or maintenance of cancer stem cells, that have the ability to self-renew and differentiate." (PMID 23283305, 2012). "Importantly, when we conducted an assessment of MELK CNA and gene expression data from 1551 TCGA woman’s cancers (1075 breast, 176 endometrial, and 300 ovarian), we found a moderate and significant correlation between CN and expression of MELK (r = 0.28, p<0.001)." (PMID 35749404, 2022). "However, as MELK is so frequently overexpressed in human cancer, finding synthetic lethal interactions with MELK overexpression would still provide a powerful means to treat cancers that overexpress MELK." (PMID 34550356, 2021). "Therefore, the role of MELK in cancer is still not fully understood." (PMID 34550356, 2021). "MELK, a highly conserved serine/threonine kinase, has been reported to be highly expressed in various types of human malignancies and exert an oncogenic role through modulating cell proliferation, apoptosis, cancer stem cell phenotypes, EMT, metastasis and treatment resistance." (PMID 33931086, 2021).
cancer (continued). "Therefore, it is unclear whether and how increased expression of MELK contributes to the fitness of cancer cells." (PMID 34550356, 2021). "However, as MELK is an E2F target gene, its increased expression could well be a side effect of increased activity of E2F activity in cancer cells." (PMID 34550356, 2021). "In addition, OTSSP167 has little effect on cancer cells with low MELK expression or normal cells." (PMID 33520717, 2020). "Genomic and pharmacological inhibition of MELK has been shown to hamper tumor growth, both in vitro and in various preclinical tumor models, further suggesting that this kinase could be a potential therapeutic target in cancer." (PMID 31861475, 2019). "As actively-growing cancers appear to up-regulate thousands of genes involved in cell cycle progression when compared to quiescent normal tissue, this observation may explain why MELK is commonly over-expressed in different malignancies." (PMID 29417930, 2018). "Therefore, inhibition of the kinase activity of MELK may disrupt MELK-mediated malignancy in cancer cells, while having a minimal effect on normal cells." (PMID 29416794, 2018). "Moreover, the over-expression of MELK has been reported to transform cells, suggesting that in addition to MELK’s putative role as a cancer dependency, it may also function as a driver oncogene." (PMID 29417930, 2018). "However, through the use of CRISPR/Cas9-mediated mutagenesis, we have demonstrated that MELK is dispensable for growth in 13 out of 13 cancer cell lines tested, and that a MELK inhibitor currently in clinical trials blocks cell division by inhibiting another target." (PMID 28337968, 2017). "We next set out to determine whether MELK was required for cancer cell fitness." (PMID 28337968, 2017). "In addition, a CRISPR/Cas9-focused study that reached similar conclusions to our study, demonstrated that off-target mechanisms contribute to the anticancer effects of OTSSP167 because WT and MELK−/− cancer cell lines were similarly sensitive to OTSSP167 treatment." (PMID 28926338, 2017). "Therefore, MELK is a promising therapeutic target for a wide range of cancers." (PMID 28938528, 2017). "However, the biological function of MELK in cancer cells is still far from full understanding." (PMID 26918358, 2016). "Moreover, expression levels of Snail (A549) and Slug (MDA-MB-231) were also drastically decreased in tumor tissues treated with the MELK inhibitor, indicating that targeting MELK could reduce cancer stem cell population in tumor tissues." (PMID 26918358, 2016). "However, little is known about the functional significance of elevated MELK expression in cancer, its role in stem/progenitor cells, or indeed whether it plays a role in development or adult organ homeostasis." (PMID 25194022, 2014). "Additionally, MELK was identified as one of the genes commonly expressed in undifferentiated cancer cells which may suggest a possible role for MELK in cancer stem cell maintenance and survival." (PMID 25365263, 2014). "Interestingly, the expression level of MELK is dramatically increased in multiple cancer tissues, which may be relevant for establishing and/or maintaining certain types of tumor." (PMID 23922895, 2013). "Thus, our results may provide the basis for designing specific MELK inhibitors for cancer treatment." (PMID 23922895, 2013).